HSD3B7 (hydroxy-delta-5-steroid dehydrogenase, 3 beta- and steroid delta-isomerase 7)
Description:
The 3-beta-HSD enzymatic system plays a crucial role in the biosynthesis of all classes of hormonal steroids. HSD VII is active against four 7-alpha-hydroxylated sterols. Does not metabolize several different C(19/21) steroids as substrates. Involved in bile acid synthesis. Plays a key role in cell positioning and movement in lymphoid tissues by mediating degradation of 7-alpha,25-dihydroxycholesterol (7-alpha,25-OHC): 7-alpha,25-OHC acts as a ligand for the G protein-coupled receptor GPR183/EBI2, a chemotactic receptor for a number of lymphoid cells (By similarity).
Synonyms: C(27)-3BETA-HSD; SDR11E3; CBAS1; PFIC4
Tractability: Small molecule: it belongs to a druggable protein family. Antibody: UniProt predicts a signal peptide or a membrane-spanning region. PROTAC: ubiquitination databases record sites on it; its protein half-life has been measured.
Gene: Protein-coding gene on chromosome 16 (30,985,143 to 30,989,154, forward strand). Ensembl gene ENSG00000099377.
Subcellular location: Endoplasmic reticulum membrane
Subcellular location (Human Protein Atlas): Lipid droplets
Pathways (Reactome):
Metabolism: Synthesis of bile acids and bile salts via 24-hydroxycholesterol; Synthesis of bile acids and bile salts via 27-hydroxycholesterol; Synthesis of bile acids and bile salts via 7alpha-hydroxycholesterol
Gene Ontology:
Molecular function: cholest-5-ene-3-beta,7-alpha-diol 3-beta-dehydrogenase activity; protein binding; 3-beta-hydroxy-Delta5-steroid dehydrogenase (NAD+) activity; oxidoreductase activity, acting on the CH-OH group of donors, NAD or NADP as acceptor
Biological process: B cell chemotaxis; bile acid biosynthetic process; steroid biosynthetic process
Cellular component: lipid droplet; endoplasmic reticulum membrane
Genetic constraint (gnomAD): Loss-of-function variants: 37 observed, 34.5 expected, observed/expected ratio (o/e) 1.07, 90% interval 0.82 to 1.41. The upper end of that interval is the gene's LOEUF score, 1.41, which puts it in group 5 of 6, group 1 being the genes least tolerant of losing a copy. Missense variants: 404 observed, 480.46 expected, observed/expected ratio (o/e) 0.84, 90% interval 0.77 to 0.91. Synonymous variants: 208 observed, 208.49 expected, observed/expected ratio (o/e) 1, 90% interval 0.89 to 1.12.
Gene-disease validity (ClinGen):
ClinGen rates the evidence that HSD3B7 causes each of these diseases.
congenital bile acid synthesis defect 1 (autosomal recessive): Definitive. Congenital bile acid synthesis defect type 1 (BAS defect type 1) is the most common anomaly of bile acid synthesis characterized by variable manifestations of progressive cholestatic liver disease, and fat malabsorption.
Homologues: Orthologues: chimpanzee HSD3B7 (99% identical), macaque HSD3B7 (96% identical), pig HSD3B7 (91% identical), dog HSD3B7 (90% identical), guinea pig HSD3B7 (89% identical), rat Hsd3b7 (88% identical), mouse Hsd3b7 (87% identical), rabbit HSD3B7 (68% identical), tropical clawed frog hsd3b7 (60% identical), zebrafish hsd3b7 (54% identical), Caenorhabditis elegans hsd-2 (24% identical), Caenorhabditis elegans hsd-3 (21% identical). Paralogues in human: HSD3B1 (38% identical), HSD3B2 (38% identical), SDR42E2 (28% identical), SDR42E1 (27% identical), NSDHL (26% identical), GALE (20% identical), TGDS (18% identical), UXS1 (17% identical), GMDS (16% identical), GFUS (14% identical).
Diseases named in the same sentence as HSD3B7 in open-access papers:
HSD3B7 is named in the same sentence as 34 diseases in open-access papers, as found by Europe PMC text mining. Sharing a sentence is not in itself a finding about the gene and the disease. The quoted sentences say what the papers report.
cholestasis (4 papers, 2013 to 2025). Impairment of the bile flow caused by obstruction within the liver, or outside the liver in the bile duct system. "It is likely that HSD3B7 deficiency acounts for 0.6% of neonatal cholestasis in our single liver center." (PMID 34627351, 2021). "This would be consistent with the previously reported incidence of all bile acid synthesis diorders accounting for about 2% of unexplained cholestasis cases, with the HSD3B7 deficiency being the most common of the disorders." (PMID 34627351, 2021). "In patients with HSD3B7 deficiency, primary bile acids are not synthesized and instead there is an accumulation of hepatotoxic 3β-hydroxy-Δ5-bile acids that leads to cholestasis that often progresses to subsequent liver failure." (PMID 34627351, 2021).
liver disease (3 papers, 2020 to 2021). "Biallelic variants in HSD3B7 cause 3β-hydroxy-Δ5-C27-steroid oxidoreductase (HSD3B7) deficiency, a life-threatening but treatable liver disease." (PMID 34627351, 2021). "Pathogenic mutations in HSD3B7 are associated with congenital bile acid deficiency type I, which is a life-threatening liver disease and manifests as hyperbilirubinemia and neonatal cholestasis." (PMID 32183854, 2020). "If untreated, HSD3B7 deficiency-associated liver disease may lead to liver failure requiring liver transplantation." (PMID 34627351, 2021). "HSD3B7 is associated with the often lethal recessively inherited bile acid synthesis defect (BASD; OMIM #607764) and with progressive liver disease characterized by malabsorption of lipids and vitamins." (PMID 34915862, 2021).
Obesity (2 papers, 2019 to 2022). Accumulation of substantial excess body fat. "In the genomic locus covering rs1549293, the chromosomal interactions with FUS and HSD3B7 were observed to form each of 54 kb and 145 kb complexes, suggesting a regulatory role by this SNP to these obesity-associated genes (Pearson correlation coefficient r is 0.78 and 0.74, respectively)." (PMID 31494266, 2019).
Alzheimer disease (1 paper, 2018). A progressive, neurodegenerative disease characterized by loss of function and death of nerve cells in several areas of the brain leading to loss of cognitive function such as memory and language. "Considering the neuroprotective effects of bile acids, a set of neurodegenerative diseases have been reported, including PD, Alzheimer's disease (AD), and Huntington's disease (HD), but the available data for HSD3B7 are limited." (PMID 29670816, 2018).
bile acid synthesis disorder (1 paper, 2021). "The medical records of a cohort of 39 unrelated patients with genetically and biochemically confirmed HSD3B7 deficiency were examined to determine whether there exist genotype-phenotype relationships in this bile acid synthesis disorder." (PMID 34627351, 2021).
Brain atrophy (1 paper, 2018). Partial or complete wasting (loss) of brain tissue that was once present. "Astrocyte expressing HSD3B7 is responsible for degradation of oxysterol, the active oxidized product of cholesterol, which can be used as a marker of brain atrophy in patients holding aging neurons with AD and HD (Leoni & Caccia, 2011; Rutkowska, Preuss, Gessier, Sailer, & Dev, 2015)." (PMID 29670816, 2018).
Cholestatic liver disease (1 paper, 2025). "There are few studies on HSD3B7, and most of them focus on patients with mutations of HSD3B7 developing a congenital BAs synthesis defect (CASD), which leads to a progressive cholestatic liver disease that is clinically responsive to primary BAs treatment." (PMID 40520367, 2025).
cognitive decline (1 paper, 2021). "Also, HSD3B7 was found for AD, which is involved with bile acid synthesis, and altered bile acid levels in relation to cognitive decline in AD has not been observed and studied until recently." (PMID 34807913, 2021).
Congenital bile acid synthesis defect type 1 (1 paper, 2026). Congenital bile acid synthesis defect type 1 (BAS defect type 1) is the most common anomaly of bile acid synthesis (see this term) characterized by variable manifestations of progressive cholestatic liver disease, and fat malaborption. "Congenital bile acid synthesis defect type 1 (CBASD1) is an extremely rare autosomal recessive metabolic disorder caused by mutations in the HSD3B7 gene, resulting in defective bile acid synthesis and accumulation of hepatotoxic intermediates." (PMID 41798580, 2026).
COVID-19 (1 paper, 2026). A disease caused by infection with severe acute respiratory syndrome coronavirus 2. "Among the genes included in these pathways, we found NQO1, CAT, RETSAT, NDUFS3, and HSD3B7, which were all already found associated with COVID-19 severity from our gene-based burden test analysis." (PMID 41500120, 2026).
haemochromatosis (1 paper, 2023). "In our study, application of GREEN-DB led to identification of candidate variants in several cases including a deep intronic variant in BMP4 in a patient with Kapur-Toriello syndrome and variants in HSD3B7 and BMP6 in a patient with neonatal haemochromatosis." (PMID 37946251, 2023).
Hyperbilirubinemia (1 paper, 2020). An increased amount of bilirubin in the blood. "In the present study, whole exome sequencing revealed additional HSD3B7 p.R110Q mutation in a case with ABCC2 p.G693R mutation, but no mutations in the other known hyperbilirubinemia-related genes in the other case with ABCC2 p.G693R mutation." (PMID 32183854, 2020).
multiple sclerosis (1 paper, 2025). A progressive autoimmune disorder affecting the central nervous system resulting in demyelination. "Modulation of EBI2 signalling and/or local concentrations of CH25H, CYP7B1 and HSD3B7 in the brain and the brain blood vessels might result in disease-modulatory effects with potential therapeutic applications in the treatment of neuroinflammatory diseases including multiple sclerosis." (PMID 39999050, 2025).
Renal cyst (1 paper, 2021). A fluid filled sac in the kidney. "Our findings show that renal lesions in the face of normal renal chemistries have a prevalence of 28.6% in HSD3B7 deficiency and the most common renal involvement was renal cysts (5/10)." (PMID 34627351, 2021).
cancer (2 papers, 2024 to 2025). A tumor composed of atypical neoplastic, often pleomorphic cells that invade other tissues. "Overexpression of HSD3B7 in hepatocytes abolished the inhibitory effect of intrahepatic delivery of miR-122 on cancer cell proliferation in c-Myc/sgTP53-induced HCC model." (PMID 40520367, 2025). "Consistently, ectopic expression of HSD3B7 in hepatocytes abolished the inhibitory effect of intrahepatic delivery of miR-122 on cancer cell proliferation in c-Myc/sgTP53-induced HCC model." (PMID 40520367, 2025). "Mechanistically, miR-122 attenuated BA production by directly targeting BA synthesis gene HSD3B7, thereby inhibiting cancer cell proliferation and HCC growth." (PMID 40520367, 2025). "Zhu and colleagues demonstrate that miR-122 deficiency in hepatocytes induces BA production by directly upregulating HSD3B7, thereby facilitating cancer cell proliferation and HCC growth." (PMID 40520367, 2025). "HSD3B7 is involved in steroid metabolism, and its role in cancer biology is increasingly recognized." (PMID 39684640, 2024).
neurodegenerative disease (2 papers, 2018 to 2025). A disorder of the central nervous system characterized by gradual and progressive loss of neural tissue and neurologic function. "Modulation of the levels of CH25H, CYP7B1 and HSD3B7 enzymes directly in the brain may thus be another way to limit the increased chemotaxis or entry of EBI2-expressing encephalitogenic immune cells into the CNS during acute inflammation, neuroinflammatory disease or neurodegenerative diseases." (PMID 39999050, 2025).
tumor (2 papers, 2024 to 2025). "Loss of miR-122 in hepatocytes promoted BA biosynthesis by enhancing the expression of its target gene Hsd3b7, thereby facilitating tumor growth of HCC cells." (PMID 40520367, 2025). "By elucidating the role of HSD3B7 in tumor progression, we provide new insights into the molecular mechanisms of ccRCC." (PMID 39684640, 2024). "Further subtype analysis of epithelial cells revealed that HSD3B7 expression was elevated specifically in tumor epithelial cells compared to normal epithelial cells, suggesting its potential role in tumor progression." (PMID 39684640, 2024). "Tumor weight, measured at the end of the 30-day observation period, was significantly lower in the LV-h-HSD3B7 group compared to controls, suggesting that HSD3B7 silencing inhibits tumor growth in vivo." (PMID 39684640, 2024). "Functional studies demonstrated that HSD3B7 promotes cell proliferation, migration, and invasion in vitro, while its silencing significantly inhibits tumor growth in vivo." (PMID 39684640, 2024). "Our findings reveal that HSD3B7 is a novel biomarker for ccRCC, providing insights into its role in tumor progression and potential as a target for therapy." (PMID 39684640, 2024). "Tumor volume was measured every seven days over a 28-day period, showing that tumors derived from HSD3B7-silenced cells grew significantly more slowly than those in the control group." (PMID 39684640, 2024). "Our trajectory analysis revealed that HSD3B7 expression was upregulated in the later stages of pseudotime, suggesting its involvement in tumor progression." (PMID 39684640, 2024). "Strikingly, overexpression of HSD3B7 in hepatocytes rescued the miR122-reduced liver tumor burden, showed by significantly elevated tumor incidence (miR-122 vs. miR-122+HSD3B7: 0% vs. 100%) and induced tumor number and size (bar2 vs. bar3)." (PMID 40520367, 2025). "Consistently, the inhibitory effect induced by overexpression of miR-122 in hepatocytes on c-Myc/sgTP53-driven tumor growth was completely blocked by forced expression of HSD3B7, indicating that the role of miR-122-HSD3B7-BA regulatory axis in paracancerous tissues on tumor growth." (PMID 40520367, 2025). "In summary, we disclose that the deficiency of miR-122 in liver parenchymal cells (hepatocytes) of the paracancerous tissues leads to the increase of BA production by accelerating the expression of its target gene HSD3B7, thereby facilitating HCC tumor cell growth." (PMID 40520367, 2025).
renal disease (1 paper, 2021). "Whether chronic exposure of the kidney to high concentrations of the atypical 3β-hydroxy-Δ5-bile acids associated with HSD3B7 deficiency can explain the renal disease is conjecture." (PMID 34627351, 2021).
HSD3B7 also shares sentences with these, for which no sentence is quoted: Parkinson disease (2 papers); Aagenaes syndrome (1); Alagille syndrome (1); Dubin-Johnson syndrome (1); dyslipidemia (1); Fanconi anemia (1); Huntington disease (1); hyperlipidemia (1); hypospadias (1); Kapur-Toriello syndrome (1); liver failure (1); lymphedema (1); metabolic disorder (1); psoriasis (1); renal carcinoma (1); vitamin deficiency (1).